APOE (apolipoprotein E)
Diseases named in the same sentence as APOE in open-access papers (continued):
Sharing a sentence is not in itself a finding about the gene and the disease.
Alzheimer disease (continued). "However, owing to natural selection, common variants typically do not impart major risk for disease, with rare exceptions of variants such as the ε4 allele of APOE in Alzheimer’s disease (AD)." (PMID 33411734, 2021). "Age and apolipoprotein E (ApoE) are the mightiest risk factors for Alzheimer’s disease (AD), but the underlying mechanisms remain unclear." (PMID 34970135, 2021). "ApoE also bears significance as the most important genetic risk factor for the sporadic form of Alzheimer's disease (AD) as carriers of the APOEε4 allele (encoding apoE4) are at a significantly higher risk of developing AD than individuals having the common APOEε3 gene variant (encoding apoE3)." (PMID 34557909, 2021). "The presence of at least one APOE ε4 allele is associated with cognitive impairment in middle aged and older adults, particularly episodic memory, which is characteristically affected in Alzheimer’s disease (AD)." (PMID 34208454, 2021). "It was identified that ApoE is a significant regulator of disease-associated microglia resulting in loss of their homeostatic-tolerogenic function in models of amyotrophic lateral sclerosis, multiple sclerosis, and Alzheimer’s disease (AD; 25)." (PMID 34369386, 2021). "We aimed to evaluate the impact of sequential anodal-tDCS on cognitive functions, functional segregation, and integration parameters in patients with MCI, according to high-risk factors for Alzheimer’s disease (AD): amyloid-beta (Aβ) deposition and APOE ε4-allele status." (PMID 34200847, 2021). "APOE ε4 is the major genetic risk factor for Alzheimer’s disease (AD)." (PMID 33600562, 2021). "In pseudo-bulk data analysis with 39 individuals, it appears that the total expression values are only mildly upregulated in disease subjects (Wilcoxon p = 0.23) even though APOE over-expression is one of the most frequently observed hallmark of Alzheimer’s disease (AD)." (PMID 34404460, 2021). "The Apolipoprotein E isoform E4 (ApoE4) is consistently associated with an elevated risk of developing late-onset Alzheimer’s Disease (AD); however, less is known about the potential genetic modulation of the brain networks organization during prodromal stages like Mild Cognitive Impairment (MCI)." (PMID 33436948, 2021). "APOE is considered a major genetic risk factor for Alzheimer’s disease." (PMID 32225014, 2020). "Given the established role of apolipoprotein E as a risk factor for Alzheimer’s disease, future studies could investigate the links between this genetic marker and well-being in the emotional and cognitive domains." (PMID 32153385, 2020). "In a series of statistical tests, we investigated whether polygenic scores are associated with a range of Alzheimer’s disease-related traits beyond the APOE locus." (PMID 32226939, 2020). "APOE ε4 (ε4/ε4) homozygotes compared with persons homozygous for risk-neutral APOE ε3 (ε3/ε3) may have up to 15 times the increased the risk for developing Alzheimer disease while APOE ε4 heterozygotes (ε4/ε3 or ε4/ε2) only have a 4 times higher risk." (PMID 32379048, 2020). "In addition to the well-established risk associated with the APOE locus, there has been considerable success in identifying additional genetic variants associated with Alzheimer’s disease." (PMID 33376986, 2020). "APOE is the major genetic risk factor for Alzheimer’s disease." (PMID 32015339, 2020). "As far as we know, this is the first study that analyzed by OCT, both in macular and peripapillary regions, all the layers of the retina in cognitively healthy subjects at high risk of developing Alzheimer’s dementia due to two risk factors: having a family history and being a carrier of ApoE ɛ4." (PMID 32503282, 2020). "APOE is the strongest genetic risk factor for Alzheimer’s disease (AD)." (PMID 33352780, 2020). "Although APOE ε4 is a risk allele for Alzheimer disease later in life, it may be associated with an attentional advantage in the early development of individuals with Down syndrome." (PMID 32986108, 2020).
Alzheimer disease (continued). "The ε2 allele of APOE is considered to be protective against Alzheimer’s disease." (PMID 32612525, 2020). "For Alzheimer’s disease, cerebral organoids were prepared from hiPSCs that harbored the disease causing variant of apolipoprotein E (APOE4), which was found to show ∼2 fold increase in the accumulation of amyloid β than control organoids that had the APOE3 gene variant." (PMID 32671050, 2020). "For example, the presence of the apolipoprotein-E4 (ApoE4) allele, a risk factor for Alzheimer’s disease (AD), may mediate the magnitude of exercise effects." (PMID 32192537, 2020). "Thus, taken together these results suggest that the previously observed associations of PHS with Alzheimer’s disease-related measures were partially driven by APOE-ε4 homozygous participants." (PMID 32226939, 2020). "In fact, APOE ε4 allele carriers with PD have been shown to have worse executive function than non-carriers and executive function has been associated with slower gait speed in otherwise healthy OAs and with increased variability and Alzheimer's disease." (PMID 33013627, 2020). "A dementia with Lewy bodies polygenic score that excluded apolipoprotein E due to its overlap with Alzheimer’s disease risk was specifically associated with at least limbic (transitional) Lewy-related pathology and a pathological diagnosis of dementia with Lewy bodies." (PMID 32912321, 2020). "The APOE gene is associated with Alzheimer’s disease, but it cannot predict individual getting it." (PMID 32572010, 2020). "Indeed, a recent study using a subset of the UK Biobank sample found that the APOE e4 genotype, a well-established risk factor for Alzheimer’s disease, is linked to increased white matter hyperintensity volume." (PMID 32032968, 2020). "Finding and targeting the factors by which APOE and its variants influence Alzheimer’s disease could have a major impact on the understanding, treatment and prevention of the disease." (PMID 32015339, 2020). "Assume we collect cross-sectional data about Alzheimer’s disease and APOE ε4 allele status in a population A. Using this data, we can develop a simple diagnostic clinical risk prediction model using logistic regression to predict the presence of Alzheimer’s disease." (PMID 32615926, 2020). "While large-scale genome-wide association studies (GWAS) have identified several genetic loci associated with Alzheimer’s disease, being a carrier of the Apolipoprotein E (APOE-ε4) allele remains the strongest genetic predictor of late-onset Alzheimer’s disease." (PMID 33143703, 2020). "Sex and the APOE ε4 genotype are important risk factors for late-onset Alzheimer’s disease." (PMID 32123170, 2020). "This genetic association study assesses whether variants near the apolipoprotein E gene (APOE) are associated with Alzheimer disease independently of ε2/ε3/ε4 genotype." (PMID 33090224, 2020). "•APOE's effect on Alzheimer's disease risk was greater in the younger group (age<80 years)." (PMID 32464432, 2020). "The apolipoprotein-E (APOE) allele frequency, an established genetic risk factor for Alzheimer’s disease, within our cohort was 76% with ε3/3 allele, 19% with one ε4 allele and 1% having ε4/4 genotype, similar to expected numbers of a representative Caucasian population." (PMID 32895386, 2020). "Moreover, recent works suggest that brain amyloid deposition is driven by the APOE locus and that a genome-wide significant variant in the Alzheimer’s disease risk gene BIN1 (rs744373) is associated with tau pathology instead of amyloid pathology." (PMID 32226939, 2020). "In this work, we investigated whether PRS or PHS are associated with Alzheimer’s disease-related biomarkers and clinical outcomes beyond the APOE locus." (PMID 32226939, 2020).
Alzheimer disease (continued). "Say that we are interested in building a diagnostic clinical risk prediction model for the presence of Alzheimer’s disease (Y = 1), using the APOE ε4 allele status (X = 1, presence; X = 0, absence) as the sole predictor of the outcome in the general population of older persons." (PMID 32615926, 2020). "The APOE‐ε4 allele is an established risk factor for Alzheimer's disease (AD)." (PMID 32472747, 2020). "Apolipoprotein E4 (APOE4) is the strongest genetic risk factor for Alzheimer’s disease (AD)." (PMID 31554665, 2019). "Notably, the ApoE ε2 allele has been previously shown to have a neuroprotective effect in Alzheimer's disease." (PMID 30991617, 2019). "Variants in the APOE gene region may explain ethnic differences in the association of Alzheimer’s disease (AD) with ε4." (PMID 31426376, 2019). "The association of strawberry intake and incident Alzheimer’s dementia was analyzed using proportional hazard models adjusted for age, sex, education, physical activity, participation in cognitive activities, APOE-ɛ4 genotype, dietary intake of other fruits, and total calorie intake." (PMID 31847371, 2019). "Also, people having both diabetes and ApoE ε4 have more than twice the risk of developing Alzheimer’s disease than do those with ApoE ε4 alone." (PMID 31675964, 2019). "Apolipoprotein E4 (ApoE4) is the major genetic risk factor for late-onset Alzheimer’s disease (AD)." (PMID 31808750, 2019). "Interestingly, the lipid-free apoE form has been shown to be co-localized with the amyloidogenic Aβ peptide in amyloid plaques in Alzheimer’s disease, whereas in particular, the apoE4 isoform is a crucial risk factor for late-onset Alzheimer’s disease." (PMID 31071995, 2019). "We were able to successfully validate the previously reported association of APOE ε4 with Alzheimer's disease (rs429358, P = 3.41 × 10−9, OR = 3.59) in our initial WES screening stage, suggesting the reliability of the current extreme phenotype sampling approach." (PMID 31032141, 2019). "We acknowledge that this approach could have a bearing on the abundance of lipids uncovered, especially as the APOE genotype is a common risk factor for age related diseases such as Alzheimer’s disease and late life cognitive decline." (PMID 30893377, 2019). "For example, apolipoprotein E (ApoE) is an endogenous ligand of α2M in blood plasma, and the binding of α2M to the ε4 isoform (the strongest known genetic risk factor for Alzheimer's disease) is much less compared to the binding of α2M to the ε2 and ε3 ApoE isoforms." (PMID 31428227, 2019). "Similarly, the APOE gene has been popularized resulting from the strong association of APOE4 alleles with Alzheimer’s disease." (PMID 31632691, 2019). "The gene APOE is associated with cognitive change and late‐onset Alzheimer's disease, and epidemiological studies have provided strong evidence that the e2 allele of APOE has a neuroprotective effect, it is associated with increased longevity and an extended healthy lifespan in centenarians." (PMID 31385390, 2019). "Despite the fact that harboring the apolipoprotein E4 (APOE4) allele represents the single greatest risk factor for late-onset Alzheimer's disease (AD), the exact mechanism by which apoE4 contributes to disease progression remains unknown." (PMID 31198491, 2019). "Apolipoprotein E (APOE) is the major genetic risk factor for late-onset Alzheimer’s disease (AD)." (PMID 30983990, 2019). "While amyloidosis is an early event in the Alzheimer disease (AD) biomarker cascade, a complex interplay among the apolipoprotein E (APOE) ɛ4 allele, educational levels, and sex may be associated with an individual’s resilience to dementia." (PMID 31642932, 2019). "Importantly, these three common human apoE isoforms show a strong genotype effect on the risk and age of onset for sporadic and late onset forms of Alzheimer’s disease (LOAD), with apoE4 being the strongest known genetic risk factor for AD." (PMID 31052389, 2019).
Alzheimer disease (continued). "Numerous studies on aging-related brain diseases show that some genes identified as risk factors for some of the most common neurodegenerative diseases - such as the allele 4 of APOE gene (APOE4) for Alzheimer’s disease (AD) - have a much earlier neuro-anatomical and neuro-physiological impact." (PMID 30677746, 2019). "Alzheimer’s disease (AD) is the most common type of dementia and, after age, the greatest risk factor for developing AD is the allelic variation of apolipoprotein E (ApoE), with homozygote carriers of the ApoE4 allele having an up to 12-fold greater risk of developing AD than noncarriers." (PMID 30700058, 2019). "Importantly, this polymorphism appears to be associated with apoE and Alzheimer’s disease (AD), as APOE4 allele represents a risk factor for this pathology." (PMID 31779116, 2019). "A total of 63 participants (90%) had additional nonactionable findings, including 60 who were found to be carriers for recessive diseases and 21 who have increased Alzheimer's disease risk because of heterozygous or homozygous APOE e4 alleles (18 participants had both)." (PMID 30487145, 2018). "Furthermore, APOE polymorphisms are the strongest risk factor for Alzheimer’s disease across genders and ethnicities with ORs for homozygous carriers of the ε4 allele between 2.2 in Latinos and 33.1 in East Asian populations." (PMID 30076208, 2018). "In this study we investigated effects of the APOE ε4 allele (which confers an enhanced risk of poorer cognitive ageing, and Alzheimer’s Disease) on sustained attention (vigilance) performance in young adults using the Rapid Visual Information Processing (RVIP) task and event-related fMRI." (PMID 29856823, 2018). "The ApoE ε4 allele is the most significant genetic risk factor for late-onset Alzheimer disease." (PMID 30517106, 2018). "APOE genotype may be associated with differences in pathways in Alzheimer’s disease, potentially through differential development and spread of tau, as well as through effects on cognitive outcomes involving non-tau-related mechanisms." (PMID 30086796, 2018). "If the association between APOE genotype and Alzheimer’s disease risk varies by race/ethnicity, then this may be the case for age-related cognitive decline as well, though no study of which we are aware has directly addressed this question." (PMID 30339707, 2018). "Thus, despite robust associations between apoE genotype and pathological cognitive aging (e.g., Alzheimer's disease), its role in healthy aging is less clear." (PMID 29452862, 2018). "The goal of this study was to test whether APOE genotype, which has been strongly implicated in Alzheimer’s disease, was associated with age-related cognitive decline among cognitively healthy older Taiwanese adults." (PMID 30339707, 2018). "The low frequency of the APOE ∊4 allele may suggest a low genetic risk of Hakka population for cardiovascular disease, Alzheimer’s disease, and other diseases." (PMID 30508003, 2018). "Additionally, there is supporting evidence for the two top associated loci in the literature; linking one locus to age-related macular degeneration, which shares many genetic similarities with Alzheimer’s disease including APOE as a risk locus." (PMID 29860282, 2018). "ApoE ε4 is an established risk factor for late-onset Alzheimer’s disease." (PMID 29896424, 2018). "Since the APOE ɛ4 allele is by far the most important genetic risk factor for Alzheimer’s disease it is plausible that a molecule resembling apoE in abundance and function is likely to play an important role in the pathogenesis of Alzheimer’s disease as well as for other endpoints." (PMID 29534716, 2018). "ApoE has been reported to be a risk factor for vascular dementia and Alzheimer’s disease." (PMID 29520099, 2018). "Among them, almost 40% of patients having Alzheimer’s disease have ApoE ε4 alleles." (PMID 30563553, 2018).
Alzheimer disease (continued). "The Alzheimer’s disease-pathogenic ε4 allele of APOE (APOE4) caused significantly lower levels of particular autophagy-critical gene transcripts compared to the non-pathogenic ε3 allele (APOE3) both in Alzheimer’s disease brains and in a transfected astroglioma cell line." (PMID 30150923, 2018). "In the brain, although apoE is involved in lipid redistribution and neuronal growth and repair, the presence of the ε4 allelic form of the apoE gene also represents the most significant genetic risk factor of developing Alzheimer’s disease." (PMID 29933361, 2018). "In addition, apolipoprotein E (ApoE), one of the most influential host risk factors for developing Alzheimer’s disease, has been implicated in the development of HAND." (PMID 29987582, 2018). "Higher chronological age as well as the APOE ε4 allele are risk factors for Alzheimer's disease." (PMID 29615896, 2018). "APOE*E4 homozygotes increase the risk of late-onset Alzheimer’s disease (LOAD) 15-fold." (PMID 29497704, 2018). "Therefore, as ApoE deficient mice are exposed to hypercholesterolemia from the beginning of early life, this model is potentially relevant to Alzheimer’s disease (AD)." (PMID 29510495, 2018). "Although harboring the Apolipoprotein E4 (APOE4) allele is a well-known risk factor in Alzheimer’s disease (AD), whether a similar risk holds true for Parkinson’s disease (PD) is currently not known." (PMID 30272057, 2018). "Although the majority of late-onset Alzheimer's disease (AD) patients are labeled sporadic, multiple genetic risk variants have been identified, the most powerful and prevalent of which is the e4 variant of the Apolipoprotein E (APOE) gene." (PMID 30296667, 2018). "Moreover, aggregation of αS was also shown to be influenced by apolipoprotein E (apoE), a major Alzheimer's disease (AD) risk factor, with apoE4 having the most robust stimulatory effect compared with other isoforms (E2 and E3)." (PMID 30595837, 2018). "Importantly, APOE is the strongest genetic risk factor for late onset Alzheimer’s Disease (AD), with E4 conferring between a 3- (heterozygous) to 15-fold (homozygous) increase in risk of AD." (PMID 29962946, 2018). "Finally, for the APOE region, we saw associations with Alzheimer’s disease, age-related macular degeneration, blood lipids, adiposity, cardiac and cognitive ageing traits." (PMID 29030599, 2017). "For Alzheimer's disease, although the univariable Mendelian randomization analyses including all variants suggested a causal effect of LDL-cholesterol on Alzheimer's disease risk, all associations attenuated to the null when the APOE variants were omitted from the analysis." (PMID 28456421, 2017). "The APOE ε4-allele, which is linked to a higher risk of cardiovascular and Alzheimer’s disease, is associated with a lower likelihood of reaching EL, whereas the ε2-allele seems to show a positive association with EL and is more frequently found in centenarians than in younger controls." (PMID 29143599, 2017). "Exposure to particulate matter (PM) in the ambient air and its interactions with APOE alleles may contribute to the acceleration of brain aging and the pathogenesis of Alzheimer's disease (AD)." (PMID 28140404, 2017). "We perform an empirical study using the Alzheimer’s Disease Neuroimaging Initiative (ADNI) cohort to discover the relationships among SNPs from AD risk gene APOE, imaging QTs extracted from structural magnetic resonance imaging scans, and cognitive and diagnostic outcomes." (PMID 28291242, 2017). "ApoE is a polymorphic protein, and there is a significant association between molecular polymorphisms and several biological processes, including Alzheimer's disease, cognitive function, immunoregulation, cerebrovascular and cardiovascular pathologies and possibly infectious diseases." (PMID 28465483, 2017). "In addition, possession of the ε4 allele of APOE is the primary genetic risk factor for developing late-onset Alzheimer's disease (AD)." (PMID 29311783, 2017).